MIF (macrophage migration inhibitory factor)
Diseases named in the same sentence as MIF in open-access papers (continued):
Sharing a sentence is not in itself a finding about the gene and the disease.
Stroke (41 papers, 2011 to 2026). Sudden impairment of blood flow to a part of the brain due to occlusion or rupture of an artery to the brain. "This provided the evidence that MIF associated with the NF-κB activation pathway plays an important role in the injury processes after stroke." (PMID 22768247, 2012). "MIF knockout mice showed activated caspase-3, neuronal loss, and infarct development during stroke." (PMID 36824264, 2023). "In addition, in stroke patients, high MIF plasma levels predicted an elevated risk for post-stroke depression." (PMID 36555097, 2022). "Overall, a reduced expression or abrogation of MIF in astrocytes may underlie an improved functional recovery, particularly long-term, after stroke." (PMID 21714902, 2011). "Based on previous in vivo and in vitro experiments, it is tempting to speculate that the upregulation of MIF in neurons underlies the observed deleterious effects, at least during the first week post-stroke in mice." (PMID 21714902, 2011). "Previous studies have found that MIF promoter activity is significantly up-regulated under hypoxia, and MIF is elevated in ischemic stroke in rodent models and patients, is associated with stroke clinical severity, and could predict severity and prognosis in patients with ischemic stroke." (PMID 36824264, 2023). "The role of MIF in stroke remains controversial - on one hand, it can induce inflammation, while on the other, it inhibits neuronal apoptosis." (PMID 40221607, 2025). "The MIF concentration in EPC-CM was 12 ng/ml, and treatment with 40 μl EPC-CM in BICAL rats showed significant protective effects in our study, consistent with the low dose of MIF administered in the stroke model." (PMID 39543689, 2024). "Brain disorders from autoimmunity, stroke, cancer and dementia are characterized by an inflammatory component, and MIF has a detrimental effect on these pathologies." (PMID 38178143, 2024). "Future studies using animal models of stroke are needed to elucidate the roles of MIF in stroke pathology and to explore its potential therapeutic implications." (PMID 39727941, 2024). "Previous studies showed that the increase of MIF was stronger than other cytokines, suggesting that it plays a regulatory role in the inflammation in stroke." (PMID 36824264, 2023). "Previous studies have shown that MIF is closely involved with stroke and Alzheimer’s disease (AD), but its relationship with CSVD and VCI is unclear." (PMID 36824264, 2023). "The broad spectrum of MIF’s actions and the complexity of MIF expression in the brain post-stroke, challenge the identification of the mechanism or mode of action of MIF in cerebral ischemia." (PMID 36824264, 2023). "In contrast, in a model of transient middle cerebral artery occlusion, MIF was found to contribute to stroke pathology in mice and neuronal death in vitro, with knockout of MIF or administration of MIF antagonist ISO-1 resulting in a smaller infarct size." (PMID 35091838, 2022). "A previous report suggested that elevated MIF and CD74 expression is linked to stroke clinical severity and causes a larger infarct size by activating and recruiting T cells." (PMID 35805977, 2022). "The MIF facilitates neurological recovery and protects brain tissue from ischemic injury, indicating a possibility of future novel therapeutic agents for stroke patients." (PMID 35805977, 2022). "MIF enhances blood brain barrier permeability and worsens stroke in some models, though it appears to protect against stroke in other studies." (PMID 31595394, 2020). "MIF inhibition has been shown to be neuroprotective in CNS disorders such as stroke, and MIF interaction with the CD74 receptor has been shown to activate astrocyte responses." (PMID 33050322, 2020). "Previously, we have shown upregulation of MIF by hypoxia in the acute phase of stroke and demonstrated the protective role of MIF in suppressing oxidative stress-induced caspase-3 activation." (PMID 31174614, 2019).
Stroke (continued). "By Western blotting and the immunohistochemistry of GFAP, we found that MIF treatment obviously increased the gliosis in ipsilateral cortex in stroke model." (PMID 29335619, 2018). "The bilateral infarct volume significantly increased in MIF (3.3 μg/kg)-treated group as compared to the control group (42.7 ± 4.9% vs. 22.6 ± 1.4%) 24 hours after stroke." (PMID 29335619, 2018). "In consistent with these studies, our findings indicated that MIF plays a pathological role in blood-brain barrier following stroke." (PMID 29335619, 2018). "To find out a possible drug target, we examined the profile of various cytokines/chemokines in the plasma of ischemic stroke patients and demonstrated that cytokine MIF was markedly elevated in the stroke patients." (PMID 29335619, 2018). "Our data from stroke patient showed that the elevation of MIF is prior to other cytokines, suggesting its regulatory role in the inflammation of stroke." (PMID 29335619, 2018). "Since the level of MIF markedly increased, ELISA kits were then used to detect the concentrations of MIF in healthy donor and stroke patients before tPA administration." (PMID 29335619, 2018). "The sex-based differences observed in this study are moreover in line with recent reports showing that female MIF KO mice have larger infarcts and increased microglial activity than WT females and male MIF KO mice after experimental stroke." (PMID 26338025, 2015). "Mif can also be grouped in this class of genes, since the upregulation of MIF after experimental stroke was shown to promote cell death." (PMID 22272763, 2012). "There is ample evidence indicating that MIF expression is increased at the transcriptional level in human stroke patients and in animal models of focal ischemia." (PMID 22768247, 2012). "Aggravation of neurological deficits by macrophage migration inhibitory factor (MIF) has been shown after experimental stroke and increases in MIF has been observed in cultured cortical neurons exposed to oxygen and glucose deprivation." (PMID 22272763, 2012). "Macrophage migration inhibitory factor (MIF) has been proposed to play a detrimental role in stroke." (PMID 21714902, 2011). "Since MIF regulates tissue inflammation, we studied the putative role of MIF in post-stroke inflammation." (PMID 21714902, 2011). "We recently showed that MIF promotes neuronal death and aggravates neurological deficits during the first week after experimental stroke, in mice." (PMID 21714902, 2011). "Based on present and previous evidence, we propose that the deleterious MIF-mediated effects in stroke depend primarily on an intraneuronal and/or interneuronal action." (PMID 21714902, 2011). "The cerebral up-regulations of IL-12 and KC were not accompanied by significant changes in the respective serum concentrations 48 h and 7 days after stroke, and similar values were obtained in WT and MIF-KO mice per condition (accordingly)." (PMID 21714902, 2011). "The broad spectrum of MIF actions and the complexity of MIF expression in the brain post-stroke challenge the identification of the exact mode or modes of action of MIF in cerebral ischemia." (PMID 21714902, 2011). "We further studied a putative effect of MIF on the spleen weight of mice during the first week post-stroke." (PMID 21714902, 2011). "We observed that MIF accumulates in neurons and astrocytes of the peri-infarct region, as well as in microglia/macrophages of the infarct core up to 7 days after stroke." (PMID 21714902, 2011). "Whereas MIF acts as an upstream regulator of inflammatory/immune reactions after stroke remains to be determined." (PMID 21714902, 2011). "Similarly, MIF protects against protein misfolding in stroke and amyotrophic lateral sclerosis (ALS)." (PMID 40508163, 2025). "The content of MIG and MIF was also significantly higher in the saliva of stroke patients." (PMID 40221607, 2025).
Stroke (continued). "The downregulation of MIF may constitute a new therapeutic approach to promote the development and recovery of nerve fibers after stroke." (PMID 40644836, 2025). "Conversely, elevation in MIF (OR: 0.8078, 95% CI: 0.6748-0.9670, PIVW: 0.0200) and haptoglobin (OR: 0.9034, 95% CI: 0.8234-0.9911, PIVW: 0.0317) was associated with a decreased risk of stroke." (PMID 39253091, 2024). "In stroke, cerebral ischemia and depression, MIF has protective as well as pathological roles." (PMID 38178143, 2024). "The role of the MIF in ischemic stroke is controversial; some studies have suggested that the MIF has a protective function in stroke, while others have shown that the MIF aggravated stroke volume." (PMID 35805977, 2022). "MIF was shown to rescue neurons from oxidative stress induced apoptosis by inhibiting caspase-3 activation, and MIF-knockout mice also had more dead neurons, as well as a greater infarct size after induction of an experimental stroke." (PMID 35091838, 2022). "Furthermore, MIF expression has been demonstrated to enhance tight junction breakdown and blood–brain barrier permeability in stroke, and MIF‐mediated processes are reported to be significantly altered in ALSP frontal cortex white matter." (PMID 33350588, 2021). "Lastly, we did not investigate all the multifaceted mechanisms of MIF in stroke; it is also associated with the metabolic adaptation of cells (glucose metabolism and anti-oxidation) in the initial phase of ischemia." (PMID 33672416, 2021). "Additionally, we sought to identify the optimal administration conditions under which MIF exerted the best neuroprotective effects in an in vitro stroke model." (PMID 33672416, 2021). "Also, previous studies found MIF promoted neuronal death and aggravates neurologic deficits after experimental stroke and ISO-1 protected against cell death." (PMID 32964038, 2020). "Interestingly, some inflammation biomarkers, such as macrophage Migration Inhibitory Factor and lipoprotein (a) had been suggested to be involved in stroke recurrence." (PMID 30969942, 2019). "Our study provides the pathological mechanism of MIF in ischemic stroke and MIF may be a good drug target for the therapy of the stroke." (PMID 29335619, 2018). "It was found that the plasma level of MIF was markedly elevated after stroke onset (n = 3)." (PMID 29335619, 2018). "MIF participates in the induction of neural stem/progenitor cells, the protection of mice female brains after experimental stroke, the mediation of the antidepressant action of exercise, and of key importance for this work, MIF plays a key role in neuroinflammatory responses." (PMID 24133408, 2013). "Moreover, MIF was shown to increase in the plasma of stroke patients within the first 3 days and positively correlated to the severity of neurological deficits." (PMID 21714902, 2011). "Up to 72 h after stroke, the baseline cellular MIF-ir is lost within the infarct core, where merely a diffuse immunoreactivity pattern could be observed." (PMID 21714902, 2011). "Our results demonstrate that MIF might be a good drug target for the therapy of stroke." (PMID 29335619, 2018). "If nothing else, it is necessary to track the variations of MIF levels over time following stroke and determine to what extent these might be related to changes of other cytokines or growth factors and ultimately, to particular depressive and other cognitive outcomes." (PMID 23675319, 2013). "In the unstimulated saliva of stroke patients, we demonstrated significantly higher levels of chemotactic factors (CTACK/CCL27, IL-8/CXCL8, MIG/CXCL9, MIF) and growth factors (basic FGF, G-CSF, HGF, LIF, VEGF) compared to controls." (PMID 40221607, 2025). "We previously observed that MIF-KO mice show a similar CD68 immunoreactivity, but a higher Gal-3 immunoreactivity within the injured brain hemisphere 7 days following experimental stroke, in comparison to WT littermates." (PMID 21714902, 2011).
Stroke (continued). "Measuring 65 plasma cytokines and chemokines revealed that individuals with stroke due to LAA, CE, and SVO have a stronger inflammatory response than those with sCeAD, particularly for the analytes HGF, SDF-1α, IL-2R, CD30, TNF-RII, IL-16, MIF, APRIL, and SCF." (PMID 38802464, 2024). "DRQ is thus our prime candidate for treatment of progressive MS as well other MIF/CD74-dependent inflammatory conditions, including stroke, methamphetamine abuse, traumatic brain injury, Alzheimer’s disease and GBM without the need for histocompatibility testing of DRQ recipients." (PMID 38178143, 2024). "In this regard, Laudanski and colleagues have observed that MIF serum levels differentiated patients with cerebrovascular events from those who did not have a stroke during the acute phase of COVID-19." (PMID 37568438, 2023). "Administering MIF after pMCAo can damage the tight junction of the BBB, increase the infarct size, and severely impair neurological function, leading to a deleterious effect on stroke." (PMID 36824264, 2023). "In contrast, GFAP levels were not decreased in MIF knockouts in an experimental stroke model and the authors concluded that MIF is part of the gliotic process but not essential for it58." (PMID 29084983, 2017). "Unfortunately, as far as we know, data have not been reported concerning MIF in relation to post-stroke depression." (PMID 23675319, 2013). "We conclude that MIF does not affect major components of the inflammatory/immune response during the first week after experimental stroke." (PMID 21714902, 2011). "Our data indicates that MIF does not affect main components of the inflammatory/immune response following stroke." (PMID 21714902, 2011). "Our data suggests that while promoting neuronal death and aggravating neurological deficits, MIF expression is not essential in driving the production of Th1/Th2 cytokines post-stroke, at least at the time-points studied." (PMID 21714902, 2011). "Moreover, considering that the extent of MIF elevation after TBI and stroke predict severity and prognosis, it is possible that inhibiting MIF might be neuroprotective after TBI." (PMID 33050322, 2020). "Notably, it has been proposed that lack of MIF in mice does not affect hallmarks of the inflammatory responses during the first week after stroke." (PMID 27926507, 2017).
asthma (40 papers, 2012 to 2025). "MIF has not only been found at elevated levels in the bronchoalveolar lavage fluid of asthma patients but its level of expression has been linked to disease severity." (PMID 39502000, 2025). "Overall, MIF levels appear to be higher in patients with asthma than in healthy individuals and are positively associated with disease severity." (PMID 39337534, 2024). "Macrophage migration inhibitory factor (MIF) and GTPase dynamin-related protein 1 (Drp1)-dependent aberrant mitochondrial fission are closely linked to the pathogenesis of asthma." (PMID 37674165, 2023). "Furthermore, MIF-deficient mice showed reduced lung inflammation and airway hyperresponsiveness in an ovalbumin-induced asthma model, while ISO-1 inhibited airway remodeling in the same model." (PMID 38145300, 2024). "Ovalbumin (OVA)-primed and inhalation-challenged asthma model mice with MIF deficiency had a reduction in the total and OVA-specific IgE, whereas MIF−/− mice infected with Schistosoma mansoni or Taenia crassiceps produced normal amounts of Th2 cytokines and IgE." (PMID 27598332, 2016). "The present study elicited two novel findings: i) osthole can ameliorate airway inflammation and macrophage activation in a murine model of asthma; ii) the inhibitive effect of osthole on macrophage activation may be associated with a NF-ĸB/MIF dependent signaling pathway." (PMID 33828480, 2021). "Human eosinophils also possess significant amounts of stored MIF, and elevated MIF levels were detected in the airways of individuals with asthma." (PMID 41159021, 2025). "This novel finding in aGVHD is in-line with studies on asthma and inflammatory bowel disease, which have also described the effect of MIF on resistance to GC therapy." (PMID 40421032, 2025). "As far as MIF is concerned, it has been reported to contribute to asthma pathogenesis and severity by promoting inflammation and cell proliferation, with genetic factors influencing its expression." (PMID 39337534, 2024). "Animal studies using models of allergic lung inflammation supported a role for MIF in asthma pathogenesis." (PMID 39337534, 2024). "Studies have found a higher frequency of the MIF −173CC genotype in children with asthma compared to healthy children." (PMID 39337534, 2024). "MIF has been associated with inflammatory and interstitial lung diseases, including COPD, asthma, and IPF." (PMID 38145300, 2024). "Conversely, the protein and mRNA expression levels of MIF gradually increased, demonstrating a positive correlation with the severity of asthma." (PMID 39176391, 2024). "In asthma, MIF has been shown to be involved in airway remodeling by promoting autophagy in ASM cells through binding to the CD74 receptor." (PMID 39337534, 2024). "In animal models of asthma and in vitro cultured ASMCs, MIF can increase autophagic activity through activation of Beclin1, leading to proliferation of ASMCs, however, the exact molecular mechanism is not yet fully understood." (PMID 37674165, 2023). "Meanwhile, MIF remarkably elevated in lung tissues of OVA-induced asthma rat model, accompanied with airway inflammation and excessive airway remodeling." (PMID 37674165, 2023). "Inhibition of MIF in vivo reduced airway hyperactivity, airway inflammation, and IgE production in a chronic mouse asthma model." (PMID 36441389, 2023). "In summary, MIF inhibitor 4-IPP treatment prevented airway remodeling in the OVA-induced asthma rat model." (PMID 37674165, 2023). "Meanwhile, in ovalbumin (OVA) or house dust mite (HDM) induced asthma rodent models, MIF levels are elevated in circulation, alveolar lavage fluid and lung tissues, and these elevations are associated with enhanced airway remodeling." (PMID 37674165, 2023). "In conclusion, we demonstrated the critical role of MIF in asthma through in vitro and in vivo experiments and elucidated that MIF promoted the proliferation of ASMCs via the ERK1/2/Drp1 axis mediated autophagy activation and consequent E-cadherin reduction." (PMID 37674165, 2023).